MYC (MYC proto-oncogene, bHLH transcription factor)
Diseases named in the same sentence as MYC in open-access papers (continued):
Sharing a sentence is not in itself a finding about the gene and the disease.
cancer (continued). "Dicerna Pharmaceuticals (Lexington, Massachusetts MA, USA), a company specializing in RNA medicines that silence genes has developed DCR-MYC, a lipid particle that incorporates synthetic double-stranded RNA to target the MYC oncogene and suppress cancer progression." (PMID 33918072, 2021). "Gene amplification is the most commonly observed alteration in cancer for the MYC gene family, and MYCN amplification is found particularly in NB in about 25% of diagnosed cases and is strongly associated with poor prognosis, thereby being a defining feature of high-risk NB." (PMID 34771690, 2021). "It is conceivable that by inhibiting MYC deSUMOylation, these SENP1 inhibitors could indirectly suppress MYC deubiquitination, thereby destabilizing MYC and exhibiting anti-proliferative effect in cancer cells." (PMID 34178666, 2021). "Under these circumstances, the fine tuning of DNA replication and transcription becomes critical and may pose an intrinsic liability in MYC-overexpressing cancer cells." (PMID 34201047, 2021). "MYC is one of the most broadly deregulated oncogenes in human cancers." (PMID 33791309, 2021). "Because MYC, PML, and PHF8 have been implicated in human cancer metastasis, we investigated whether they were involved in CCL7 upregulation in OC-MQ." (PMID 34206004, 2021). "Indeed, as highly proliferating cancer cells require enhanced lipid production, c-MYC induces SREBP and together they collaborate to activate fatty acid (FA) synthesis and drive FA elongation from glucose and glutamine." (PMID 35008356, 2021). "Thus, the interplay between MYC and P-TEFb can contribute to the establishment of tumor-specific gene expression signatures in cancer cells." (PMID 34146121, 2021). "However, this cooperation of MYC with HIF has mainly been reported to occur in cancer cells with high MYC levels, which is a very different setting from a young to middle age population cohort or wild-type mice studied here." (PMID 34261659, 2021). "ESCs and cancer cells share MYC-module activity, raising the hypothesis that cancer cells can reactivate the ESC gene signature." (PMID 34439740, 2021). "Therefore, MYC has been recognized as the ‘most wanted’ target in cancer for decades, but most efforts have met with inescapable off-target toxicity." (PMID 34676047, 2021). "c-MYC is expressed in the agnospheres derived from the most aggressive cases, diagnosed as “poorly differentiated carcinomas of unknown origin”." (PMID 33941777, 2021). "MYC could be one of the factors providing cancer cells with their necessary traits required for a successful metastatic progression." (PMID 33081056, 2020). "Moreover, the accumulation of β-catenin in the nucleus and the promotion of several oncogenes’ transcription, including c-MYC, contributes to carcinogenesis and cancer cells progression, since c-MYC involvement in cell cycle." (PMID 32560347, 2020). "miR-34a and let7a are also targets of MYC repression establishing a feedback loop that aggravates and perpetuates the effects of MYC overexpression and may thus contribute to cancer progression." (PMID 32549409, 2020). "In addition, we detected the mRNA expression of cancer stem cell makers, including c-MYC, CD44 and CD133, and found that their expression were increased in TRIP6-transduced ZR-75-30 and MDA-MB-231 cells but were decreased in TRIP6-silenced cells." (PMID 32082081, 2020). "In addition, cancer cells with overexpressed MYC oncogene are reported to be synthetically lethal to DNA-PK inhibition, supposedly due to increased MYC-driven DNA damage and the cancer cell reliance on the DDR pathways." (PMID 32883316, 2020). "Thus, our studies have identified a new small molecule, the benzofuran containing MYC G4 stabilizer D089 which can be used for further studies of pyroptosis and senescence in cancer models." (PMID 33066043, 2020). "As such, MYC-driven cancers frequently exhibit strict dependency on glutamine metabolism." (PMID 32651356, 2020).
cancer (continued). "Cell-based assays indicated an IC50 in the 10–20 μM range in MYC-dependent cancer cells." (PMID 32331235, 2020). "It has been reported that MYC is a transcription factor for CD47 in cancer cells." (PMID 32296015, 2020). "Two factors can be selected for in rearrangement-driven cancers: oncogenic biochemical function in the case of a resulting fusion protein and aberrant expression levels of a proto-oncogene (such as MYC or GFI1) via enhancer hijacking." (PMID 32416589, 2020). "MYC is a proto-oncogene and a major driver of many human cancers." (PMID 32570740, 2020). "However, MYC is a nuclear oncogenic transcription factor playing a pivotal role in human carcinogenesis, being highly expressed in more than 80% of human cancers." (PMID 32610656, 2020). "MYC is a critical transcription factor that regulates transcription of downstream target genes, leading to enhanced proliferation and metastasis of diverse cancers." (PMID 32685003, 2020). "Kinetic theory and experiments indicate that MYC activates at least two steps in the transcription-cycle to explain the non-linear amplification of transcription that is essential for global, supraphysiological transcription in cancer." (PMID 32715994, 2020). "MYC also affects ROS production by impinging on cancer cell metabolism." (PMID 31819197, 2020). "(d) Correlation of MYC+TWIST1 expression with TAM markers in TCGA pan-cancer cohort and HCC cohort." (PMID 31933479, 2020). "MYC illustrates the opposite trend, instead being heavily amplified across cancer types." (PMID 33266490, 2020). "Finally, we show that in cancer cell lines there is a strong correlation between MYC and UBR5 amplification, suggesting a selection pressure for co-amplification and a potential vulnerability in this subpopulation towards loss of function of UBR5." (PMID 33208877, 2020). "Interestingly, in cancer cell lines with amplified MYC expression, depletion of UBR5 resulted in reduced cell survival, as a consequence of MYC stabilization." (PMID 33208877, 2020). "Indeed, CDK7 was found to be associated with the important transcription factor MYC and with the STAT3 and β-catenin pathways which play crucial roles in tamoxifen resistance, stemness, and cancer progression." (PMID 32340192, 2020). "To summarize, MYC is undoubtedly an important player in cancer aggressiveness and progression." (PMID 33081056, 2020). "However, CDK9-specific inhibitors, such as BAY 1143572 (NCT01938638), are beginning to enter clinical trials in patients with advanced cancer and will evaluate MYC expression as a biomarker." (PMID 33322239, 2020). "Earlier reports suggest that micronuclei may accompany self-replicating chromatin units, such as double minute (DM) chromosomes containing oncogenic MYC, sometimes resulting in the active extracellular release of these structures from cancer cells." (PMID 32444772, 2020). "Given that inhibition of BET by small molecule JQ1 resulted in suppressing MYC expression and thereby induce cell death, a pediatric cancer trial is currently underway including assessing the BET inhibitor BMS-986158 in MB with MYC/MYCN amplification (NCT03936465)." (PMID 32164294, 2020). "Additionally, CIP2A mRNA and protein content is regulated by MYC, creating a positive feedback loop between the two oncogenes in cancer." (PMID 32110991, 2020). "The expression of MYC level in different types of cancers was conducted by the Oncomine database." (PMID 33193630, 2020). "Furthermore, the colon cancer-associated transcripts 1 and 2 (CCAT1 and CCAT2, respectively), mapping upstream of the MYC locus at ≈515 kb and 333 kb, respectively (RefSeq on hg38 genome release) have been also reported to regulate Myc." (PMID 33142861, 2020). "Consequently, deregulated MYC makes cancer cells addicted to glutamine and deprivation of glutamine causes cell death." (PMID 33251216, 2020).
cancer (continued). "MYC expression is tightly controlled at transcriptional and post-transcriptional levels in healthy cells; however, MYC expression is frequently dysregulated in human cancers." (PMID 33291213, 2020). "In addition, we replicated experiments performed in previous reports that showed that miR-145 regulates important processes in cancer cells, such as cell proliferation, migration and invasion, by controlling c-MYC and VEGF protein levels." (PMID 33081171, 2020). "Targeting MYC is found to be a novel strategy in defeating such cancers." (PMID 31932624, 2020). "As a member of the critical family of m6A readers that identify the consensus GG(m6A)C sequence, IGF2BP3 participates in thousands of mRNA posttranscriptional modification through enhancing the stability and accommodation of its target mRNA (like MYC) in cancer biology." (PMID 32710725, 2020). "This functional connection between MYC and NSD3S provides a novel link between two oncogenic proteins that are known to drive cancer cell survival and may serve as a promising target for therapeutic intervention in MYC-driven tumors." (PMID 31638140, 2020). "The MYC oncogene and its target genes contribute to the genesis of many human cancers." (PMID 32175271, 2020). "These upregulated target genes are enriched for the pathways involved in metabolism (e.g., SLC3A2, SLC7A5) and mitochondrial gene expression (e.g., PNPT1), consistent with previous studies, demonstrating that elevated MYC/MYCN induces metabolic reprogramming in cancer cells." (PMID 32060267, 2020). "A transcriptional regulatory feedback loop between MYC and SWI/SNF could be a major factor contributing to the aggressiveness of MYC dependent cancers." (PMID 31932624, 2020). "CUL1 and c-MYC both show synergistic function in cancers and can act as oncogenes." (PMID 32811853, 2020). "Besides promoting cancer progression and metastasis, MYC has a bivalent role in regulating tumorigenesis and cell invasion." (PMID 32098783, 2020). "MYC is a desirable therapeutic target for several types of cancer." (PMID 32110991, 2020). "The c-MYC pathway is well known to enhance the cancer cell growth and proliferation." (PMID 33489906, 2020). "BRD8, an accessory subunit of human NuA4-HAT complex, may function in embryonic or cancer stem cell reprogramming via the c-MYC pathway." (PMID 32927435, 2020). "Likewise, different reports propose that the increase in metastatic behavior of cancer cells over-expressing MYC is derived from its ability to induce cell motility through the direct or indirect modulation of the molecular markers of EMT." (PMID 33081056, 2020). "Similar to SEs in many other cancers, PEL SEs were linked to key oncogenes such as MYC." (PMID 33298918, 2020). "The MYC transcription factor family is one of the central and most studied groups in cancer." (PMID 33292222, 2020). "Similarly, cancer stem cells, which are inherently resistant to therapy, can also adopt glycolysis for energy production depending on MYC expression." (PMID 32466502, 2020). "In addition to DNAI1, another three genes, MYC, PROSER2, and FATE1, have been reported to be associated with several cancers." (PMID 33082842, 2020). "The CRISPRi-PVT1 did not induce an increase in MYC transcription in some cell types, and not all cancers examined had mutations of the PVT1 promoter." (PMID 32117705, 2020). "Furthermore, MYC and TWIST1 cause metastasis by switching a transcriptional program in cancer cells that induces cytokines." (PMID 33081056, 2020). "Differential metabolic requirements within specific cancer types might dictate the final outcome of MYC regulation of glutamine catabolism." (PMID 32651356, 2020).
cancer (continued). "Moreover, using PPI networks, key cancer regulators such as MYC, VEGFA, AKT1, CDKN1A, RHOA, and PTEN are identified." (PMID 33281862, 2020). "The c-MYC-eIF4E axis has also been extended to cancer immunotherapy." (PMID 32759815, 2020). "This conclusion would then lead to the hypothesis that the repression might be important for understanding the regulation of MYC expression during cancer." (PMID 32501500, 2020). "Although much is known about MYC on one hand and lncRNA on the other in cancers, their significance of their regulatory interaction with each other in hematological malignancies is still largely unknown." (PMID 33134177, 2020). "In addition, c-MYC is known to enhance the conversion of proline from glutamine by stimulating growth and proliferation of cancer cells." (PMID 32824561, 2020). "Interestingly, HIF2α-induced stabilization of MYC/MAX heterodimer is much stronger than HIF1α-induced degradation of MYC in cancer cells, leading to MYC activation under hypoxia." (PMID 33251216, 2020). "The observation that Fusobacteria upregulated STAT3, JAK1, and MYC indicated that Fusobacteria infection might enhance cancer cell survival through modulation of these oncogenes, which are well implicated in pathways that promote tumorigenesis." (PMID 33391626, 2020). "While MYC is a “pan-cancer” oncogene, NOTCH1 is more “T-ALL-specific”." (PMID 32380791, 2020). "Interestingly, elevated MYC was independently identified as the main driver of stemness in all of these cancer types." (PMID 33092283, 2020). "Therefore, it is considered one of the most potent cellular oncogenes, and MYC over-expression is a frequent event in many types of human cancers." (PMID 33081056, 2020). "Interestingly, MYCBP is the binding protein of MYC, an important oncogene well characterized in cancer." (PMID 33327559, 2020). "Eight cancers (~ 10%) were defined as MYC hyperactivated by all three MYC signatures." (PMID 33099868, 2020). "Thus, it’s very difficult to make MYC antibodies and get them to function in the nucleus for cancer treatment." (PMID 32651356, 2020). "A salient feature of spindle MBCs, which are highly proliferative and exhibit pathological evidence of EMT with elongated cancer cells, is upregulated expression of E2F and MYC pathway proteins, ribosomal proteins and transcriptional and translational processes." (PMID 32265444, 2020). "However, IGF2BP1 and MYC mRNA expression appear barely correlated in most cancers and IGF2BP1 ablation results in conserved and exclusive impairment of G1/S transition." (PMID 32761127, 2020). "Therefore, the therapeutic efficacy of splicing modulation by targeting splicing factors and specificity for MYC-driven cancers should be further investigated." (PMID 32481522, 2020). "Dysregulation of MYC protein levels through MYC overexpression or reduced degradation may lead to multiple diseases, including cancer." (PMID 31638140, 2020). "c-MYC is a strong oncogenic driver in many cancers including acute leukemia." (PMID 32151059, 2020). "Downregulation of MYC will induce cancer cell quiescent and apoptosis." (PMID 33170148, 2020). "Thus, MYC expression is frequently enhanced in cancer leading to elevated MYC RNA and protein expression." (PMID 32927768, 2020). "This pivotal need for intracellular amino acids is reflected in the increased expression of amino acid transport systems in the majority of cancers, which is regulated by various transcription factors such as c-MYC, hormone receptors, and nutrient starvation responses." (PMID 32200487, 2020). "Also, iBET-BD1 was enough to displace BRDs from chromatin, even at MYC super enhancers in cancer cells." (PMID 33585252, 2020). "MYC signaling also plays pivotal roles in regulating cancer cell metabolism and vasculogenesis." (PMID 33251216, 2020). "GPAT is upregulated in many cancers in a MYC-dependent manner." (PMID 33335484, 2020).
cancer (continued). "CYRI‐B lies near the gene encoding c‐Myc on human chromosome 8 region q22, so it may be a passenger amplification along with MYC in cancer." (PMID 32057095, 2020). "Thus, CPF suppresses proliferative switching through transcriptional suppression of FACT and the c‐MYC, providing a new insight into therapeutic target and intervention method in impeding cancer recurrence." (PMID 31960591, 2020). "Due to this and the fact that MYC can directly increase CHK1 gene expression in some cancers, we hypothesized that BETi/OTX-015 would down-regulate MYC and contribute to decreased CHK1 protein levels." (PMID 32859084, 2020). "It is important to note that CCND1 and c-MYC are the classic proto-oncogenes involved in regulation of cell cycle and proliferation, thus playing a critical role in development of various types of malignant tumors." (PMID 33007980, 2020). "Such high-MYC output in cancer may also be enforced by a panoply of pathologically activated super-enhancers." (PMID 33005010, 2020). "The intersection of differentially expressed genes (DEG) and our list of candidate genes, resulted in 12 elements including cancer associated genes (NRAS, MYC, and VEGFA), circadian drug targets (SOD2 and CES2) and core-clock and ECCN genes (AHR, CREB1, CSNK2A1, NFIL, NPAS2, NR1D1, and PER3)." (PMID 32295075, 2020). "Indeed, PVT1 inhibition can induce cell apoptosis, even in PVT1-overexpressing cells, whereas MYC silencing does not produce the same effect, suggesting different mechanisms of PVT1 and MYC cooperation in different cancers." (PMID 33142861, 2020). "In addition, the down-expression of these genes were enriched with MYC target, which was also an important oncogene target in cancer development." (PMID 32859214, 2020). "MYC is involved in a variety of biological processes in cancer cells." (PMID 33099868, 2020). "Despite its attractiveness as a cancer target, MYC has been considered “undruggable” and remains outside reach of pharmacological regulation, mainly due to its nuclear localization, lack of a defined ligand-binding site, and large protein-protein interaction (PPI) surface." (PMID 33298911, 2020). "Hence, this result suggests that BASP1‐mediated inhibition depends on actual MYC and CaM levels in human cancer cells." (PMID 31944520, 2020). "The interaction of HIF-1 and c-MYC directs cancer cells to glycolysis by upregulating the glucose transporter 1 (GLUT1) which increases glucose uptake, and hexokinase 2 (HK2) which catalyzes the first step of glycolysis, and PDK1 which suppresses mitochondrial respiration." (PMID 33028364, 2020). "Studies have suggested that the spliceosome component may be a therapeutic entry point for aggressive MYC-driven cancers." (PMID 33170908, 2020). "However, a study in MYC inducible cancer cell lines has shown that highly proliferating MYC expressing cells require active OxPhos together with increased glycolysis to drive their fast cell cycle progression." (PMID 33585251, 2020). "Thus, it is worth examining the expression of MYC-related E3 ligases when MYC expression is evaluated in TRIB3-depleted cancer cells." (PMID 33298911, 2020). "Our finding reveals a complex interplay between SWI/SNF and MYC in different cell types and may be an important factor to be considered for addressing the aggressiveness of MYC dependent cancers." (PMID 31932624, 2020). "Dysregulation of IGF2BPs could result in abnormal accumulation of oncogenic products such as MYC in human cancer cells." (PMID 32245489, 2020). "RFX1 can play an anti-cancer role by down-regulating the original oncogene c-MYC." (PMID 32799626, 2020). "MYC does not require changes to the protein sequence to cause cancer; it instead becomes an oncogene through abnormal expression." (PMID 33193630, 2020). "Our study is the first to show OCT4 as an upstream regulator of c-MYC in human cancer." (PMID 32409685, 2020). "MYC is deregulated in > 50% of human cancers, rendering it an attractive drug target." (PMID 33208877, 2020).